RN7SL250P (RNA, 7SL, cytoplasmic 250, pseudogene)
Gene: Miscellaneous RNA gene on chromosome 8 (54,420,468 to 54,420,725, forward strand). Ensembl gene ENSG00000244107.
Homologues: Orthologues: chimpanzee Metazoa_SRP (98% identical), macaque Metazoa_SRP (94% identical), dog Metazoa_SRP (67% identical), pig Metazoa_SRP (67% identical). Paralogues in human: RN7SL33P (85% identical), RN7SL1 (85% identical), RN7SL3 (84% identical), RN7SL18P (84% identical), RN7SL2 (84% identical), RN7SL322P (84% identical), RN7SL357P (83% identical), RN7SL122P (83% identical), RN7SL448P (83% identical), RN7SL575P (83% identical), RN7SL597P (83% identical), RN7SL220P (82% identical), and 705 more.